INS (insulin)
Diseases named in the same sentence as INS in open-access papers (continued):
Sharing a sentence is not in itself a finding about the gene and the disease.
Insulin resistance (continued). "Our study showed that the fasting insulin level and insulin resistance were significantly high in the MetS and obese groups and that the TOS value in the MetS group was higher than that in both the control and obese groups." (PMID 25241610, 2014). "Afro-Americans have significant hepatic insulin resistance compared to peripheral insulin sensitivity." (PMID 24555815, 2014). "As the secondary messenger of insulin, this molecule increases metabolic effects of insulin and it is related to insulin resistance." (PMID 24812607, 2014). "Our data showed that vildagliptin and metformin improved insulin resistance and metabolic parameters as well as oxidative stress in obese-insulin resistant rats." (PMID 25036861, 2014). "Classical PTPs such as PTP1B and T-cell PTP have been identified as critical regulators of insulin and leptin signalling, serving important roles in the development of obesity and insulin resistance." (PMID 25375135, 2014). "Both Type I and Type II diabetic patients use insulin, however late stage Type II diabetes patients require large doses of insulin as they develop insulin resistance." (PMID 25270715, 2014). "Pancreatic β-cells are key players in the development of T2DM, as they are required to secrete increasing amounts of insulin so as to compensate for increasing insulin resistance." (PMID 25297556, 2014). "Decreased insulin clearance is another regulatory mechanism, in addition to increased insulin secretion, that compensates for insulin resistance." (PMID 24932224, 2014). "Elevated sympathetic activity relative to parasympathetic activity can induce a higher FFA release from adipose tissue and result in decreased insulin-stimulated glucose uptake in target organs that contribute to the development of insulin resistance." (PMID 25024728, 2014). "Fasting plasma insulin level of control mice was significantly higher than mice treated with atorvastatin (P < 0.05), which indicated more severe insulin resistance state." (PMID 24950764, 2014). "OPN-deletion protects against insulin resistance caused by HFD, as evidenced by the improvement in insulin levels, HOMA and IPITT." (PMID 24871103, 2014). "Chronic activation of AMPK (6-8 weeks) has shown a significant decrease in both fasting plasma glucose and insulin in both animal models of insulin resistance." (PMID 24460834, 2014). "This contribution of inflammation in promoting insulin resistance is not only observed in the WAT but also in other insulin target tissues such as liver and skeletal muscles." (PMID 25337938, 2014). "Individuals with impaired glucose tolerance (IGT) have muscle insulin resistance along with defective late insulin secretion." (PMID 25960777, 2014). "Elevated levels of plasma FFA are considered as a causal factor for insulin resistance and reduction in serum FFA levels improves insulin sensitivity in humans as well as in animal models of disease (Ahrén 2001)." (PMID 24936385, 2014). "HOMA is a computational method for assessing β-cell function and insulin resistance and is widely used to assess the insulin sensitivity and resistance as a surrogate index." (PMID 25013775, 2014). "This nongenetic diabetic mouse model manifests the metabolic characteristics of human T2D, including moderate levels of hyperglycemia, hyperlipidemia, insulin resistance, impaired insulin secretion, and reduced β-cell mass." (PMID 25147566, 2014). "C3H-Chr 14NSY mice showed significantly impaired insulin sensitivity, but normal insulin secretion, indicating that the main effect was due to insulin resistance." (PMID 25167881, 2014). "In an experimental study in rats, defects in insulin-stimulated tyrosine phosphorylation of insulin receptor substrates-1 and −2 by high levels of circulating fatty acids contributed to insulin resistance." (PMID 25153887, 2014).
Insulin resistance (continued). "Before birth, GK rats present decreased β-cell mass and low plasma insulin as compared with Wistar control rats, proceeding to hyperglycemia and insulin resistance around weaning (3-4 weeks of age)." (PMID 25097548, 2014). "After application of the euglycemic-hyperinsulinemic clamp, it was found that the HP-fed rats exhibited insulin resistance after fed for 16 weeks, as shown by the higher glucose infusion rate upon extron insulin stimulation in comparison with the CT rats." (PMID 24422660, 2014). "In humans, TRIB3 has also been associated with insulin resistance and T2DM, accompanied by enhanced inhibition of insulin signalling and AKT/PKB activation in different tissues, including the β cells." (PMID 24650557, 2014). "The HOMA-IR calculation indicates insulin resistance among the Pb-exposed males signifying an abnormal response to insulin in order to properly transport glucose." (PMID 25105421, 2014). "Subsequent H2O2 production and emission oxidize redox-sensitive cysteine residues that initially potentiate insulin action, yet potentially lead to insulin resistance via chronic inhibition of phosphatases and aberrant kinase activity." (PMID 24672550, 2014). "Skeletal muscle is one of the primary tissues responsible for insulin-stimulated glucose uptake, and reduced mitochondrial function plays an important role in the development of insulin resistance coupled with obesity." (PMID 25114710, 2014). "Insulin resistance is a decrease in the ability of insulin to exert its biological action at different glucose concentrations." (PMID 24741627, 2014). "Recently, it has been demonstrated that L-carnitine supplementation can improve insulin resistance and glucose disposal in insulin-resistant humans and rats." (PMID 25424121, 2014). "Since insulin secretion shows a compensatory increase in the presence of insulin resistance, true beta cell function should be evaluated based on insulin secretion adjusted by insulin sensitivity, the so-called disposition index." (PMID 26237486, 2014). "Pregnant women who develop gestational diabetes are assumed to have a compromised beta cell capacity unable to adapt to the increased demand of insulin due to target-organ insulin resistance." (PMID 25215961, 2014). "The homeostasis model assessment was calculated from FBG and plasma insulin levels as an index of insulin resistance (HOMA-IR) and pancreatic β cell function (HOMA-β)." (PMID 25283478, 2014). "Similar to insulin resistance, insulin secretion also shows evidence of racial differences, being reduced in Asians compared with Europeans." (PMID 24744783, 2014). "Several recent studies have reported that impaired insulin secretion was more prominent than insulin resistance, even in the status of impaired glucose tolerance, in Asian subjects." (PMID 25138993, 2014). "Elevated FFA levels decrease insulin sensitivity in trained and sedentary humans, and induce insulin resistance in both skeletal and cardiac musles." (PMID 25144649, 2014). "It has been well documented that regular exercise can alleviate or protect against type 2 diabetes by enhancing insulin sensitivity in peripheral tissues, and it can protect against insulin resistance in the high‐fat (35.5–60% from kcal) feeding model." (PMID 24997069, 2014). "Our study shows that tissue-specific markers of IR offer a new approach to evaluate the role of insulin resistance beyond and above fasting insulin level in the prediction of incident type 2 diabetes and cardiovascular disease." (PMID 25310839, 2014). "In conclusion, the present study revealed that higher 25(OH)D concentration and CRF levels were negatively correlated with levels of fasting insulin and insulin resistance in middle-aged and elderly Japanese men." (PMID 25551248, 2014).
Insulin resistance (continued). "The aqua aerobics program contributed to positive changes in lipid metabolism, anthropometric variables, as well as the fasting insulin, glucose levels and insulin resistance index in women with abdominal obesity." (PMID 25114733, 2014). "There is ample evidence, in numerous species, that glucocorticoids result in increased serum insulin and glucose, decreased insulin-mediated glucose uptake, and insulin resistance." (PMID 25210711, 2014). "The objective of this study is to evaluate the anti-insulin resistance bioactivity of 16 selected traditional Chinese medicinal plants in DXMS-induced IR (insulin resistant) HepG2 cells." (PMID 25089237, 2014). "For example, hyperactive sympathetic tone can induce an insulin antagonist effect that results in insulin resistance." (PMID 25024728, 2014). "In correlation analyses, the significantly positive relationships between insulin resistance markers (fasting insulin and HOMA-IR), lipid profiles (triglyceride and HDL), and recovery heart rate were found after adjusting for age and sex (data not shown)." (PMID 24723950, 2014). "In insulin resistance state, plasma insulin levels increase to maintain a constant plasma glucose level." (PMID 24523637, 2014). "Generally, both animal models of insulin resistance appear to be suitable for testing insulin-sensitizing agents." (PMID 24415067, 2014). "On the other hand, several previous in vitro and in vivo reports demonstrate also an involvement of CT-1 in insulin sensitivity, though, a deleterious effect of CT-1 on the development of insulin resistance." (PMID 25025664, 2014). "On the average, many studies show that, when considered in light of the degree of insulin resistance, all the indexes of insulin secretion appear to be decreased with age, indicating decreased beta-cell secretory reserve." (PMID 25232350, 2014). "It has been demonstrated the synthetic LXR agonists ameliorated insulin resistance by restoring the insulin-Akt signalling cascade and preventing JNK activation in adipocytes." (PMID 25416469, 2014). "Accordingly, although results from meta-analysis reported that fruit juices did not significantly affect the concentrations of fasting glucose and insulin, they significantly increased the homeostatic model assessment insulin resistance index (HOMA-IR) values." (PMID 25610461, 2014). "Type 2 diabetes (T2D) is one of the most common chronic metabolic diseases characterized by insulin resistance and the decrease of insulin secretion." (PMID 24565181, 2014). "Homeostasis model assessment-insulin resistance and Quantitative Insulin Sensitivity Check Index were used for estimating insulin sensitivity." (PMID 25247153, 2014). "We observed inverse correlations between serum adiponectin level and bodymass index, homeostasis model assessment insulin-resistance score, insulin level, fast-ing glucose level, and prolactin level (p=0.001, p=0.02, p=0.04, p=0.02, and p=0.005,respectively)." (PMID 24520503, 2014). "Ptprt−/− mice demonstrate decreased peripheral insulin resistance as well as lower levels of blood insulin and glucose." (PMID 24949727, 2014). "In some other studies, ferritin is correlated with the measures of insulin resistance, such as elevated glucose and insulin levels." (PMID 25162051, 2014). "It is unlikely that fasting glucose levels relate to protection from insulin resistance since terminal insulin concentrations were elevated after 6 weeks on ad libitum HF diet." (PMID 24518863, 2014). "Insulin resistance is characterized by an impaired ability of insulin to stimulate glucose uptake into insulin sensitive tissues (i.e., muscle and adipose tissue) in all species." (PMID 24977043, 2014). "Further, computations of insulin resistance and sensitivity derived from glucose and insulin measurements consistently demonstrated improvements (HOMA-IR, ISI0,120, Matsuda index)." (PMID 24981579, 2014).
Insulin resistance (continued). "Type 2 diabetes mellitus (T2DM) is a heterogeneous and complex disease characterized by insulin resistance in adipose tissue, liver, and skeletal muscle, as well as impaired pancreatic insulin secretion." (PMID 25436770, 2014). "In comparison to women without MetS, a high-normal serum concentration of T3 in women with MetS is positively associated with reduced glycaemia and CVR but negatively related to body mass index (BMI), insulin, insulin resistance, and HDL-C." (PMID 24936390, 2014). "Aldosterone also plays a crucial role on systemic and vascular insulin resistance, i.e. the inability of a tissue to respond to insulin." (PMID 25352918, 2014). "The decrease in liver InsR and IRS expression is in accordance with the impairment of the hepatic insulin pathway and represents the therapeutic targets of insulin resistance." (PMID 25160038, 2014). "Insulin resistance index (HOMA-IR) is fasting insulin (mU/mL) × fasting plasma glucose (mmol/L)/22.5." (PMID 24772445, 2014). "T1D develops on the basis of autoimmune destruction of pancreatic beta cells, which results in insulin deficiency, whereas the hyperglycemia in T2D results from a combination of impaired insulin secretion and insulin resistance." (PMID 24904693, 2014). "Increased secretion of adipokines including leptin, Acrp30 and resistin from adipocytes can modulate insulin signaling and lead to insulin resistance." (PMID 24821545, 2014). "It derived its name from the original observation that it induced insulin resistance in mice (resist-in: resist insulin) and it was downregulated in mature murine adipocytes cultured in the presence of insulin sensitizing drugs such as thiazolidinediones." (PMID 24692844, 2014). "Inflammation - induced inhibition of the insulin signaling pathway can lead to insulin resistance and contribute to the development of Type 2 DM." (PMID 25393696, 2014). "Reduction in insulin resistance is known to be one of the primary metabolic adaptations of fitness, which leads to improvement in insulin sensitivity and glucose tolerance for skeletal muscle and throughout the body." (PMID 24454926, 2014). "Once insulin resistance develops, the body responds through compensatory mechanisms designed to maintain insulin signaling." (PMID 25259572, 2014). "The Gpr120 deficient mice, showed impaired glucose tolerance, increased insulin secretion, as well as hepatic and skeletal muscle insulin resistance on normal chow diet (containing exogenous ω-3 lipids) despite having unaltered body weights." (PMID 25541716, 2014). "In the SHR rat model investigated herein, as in human insulin resistant states such as obesity and fatty liver, insulin resistance is coupled to increased hepatic lipid content, FFA oxidative activity/capacity, and gluconeogenic activity/capacity." (PMID 25937836, 2014). "Our results also demonstrate that fasting serum insulin levels and the insulin resistance marker HOMA-IR were lower in the high fitness group than the low fitness group despite the high fitness group having a higher visceral adiposity." (PMID 24454926, 2014). "On the other hand, increasing insulin resistance and subsequent insulin hypersecretion eventually worsen the level of beta cell failure." (PMID 25174260, 2014). "T2D is characterized by high blood glucose levels due to insufficient insulin secretion, insulin resistance, and impaired insulin action." (PMID 24527048, 2014). "This clarification measures the movement of the insulin responsive glucose transporter GLUT4 to the cell surface, which is an essential step for insulin-responsive glucose transport in muscle that becomes defective in insulin resistance." (PMID 25140189, 2014). "Weighted mean differences were calculated for net changes in the levels of fasting glucose, fasting insulin, hemoglobin A1c (HbA1c), and homeostatic model assessment of insulin resistance (HOMA-IR) using fixed- or random-effects model." (PMID 24743260, 2014).
Insulin resistance (continued). "Short-term supplementation with pioglitazone, an insulin sensitizing agent that stimulates PPAR-γ, to offspring from obese mothers attenuated the programmed obesity and insulin resistance associated with maternal obesity." (PMID 24967364, 2014). "In the present study, we generated a mouse model mimicking human type 2 diabetes with impaired insulin secretion and insulin resistance." (PMID 24968071, 2014). "The current study illustrates the ability of macrophage A2bAR to regulate glucose and insulin homeostasis, and protect against the development of insulin resistance." (PMID 24892847, 2014). "It is widely accepted that one of the characteristics of normal pregnancy is a state of insulin resistance with a relative intolerance to dietary carbohydrates and a compensatory increase in insulin secretion from the beta cells in the pancreas." (PMID 25215961, 2014). "It has been reported that hyperglycemia and hyperinsulinemia activate the O-GlcNAcylation of proteins included in the insulin signaling pathway, facilitating insulin resistance." (PMID 25346723, 2014). "Consistent with this view, a recent study showed that the expression of IRS2 as well as insulin-mediated Akt phosphorylation in renal tubules is preserved in Zucker fatty rats that show marked insulin resistance due to defective leptin signaling." (PMID 24982885, 2014). "So far, genetic predisposition to GDM has been reported for variations in genes involved in insulin resistance and insulin secretion." (PMID 24695443, 2014). "What's more, how about the relation between insulin secretion or insulin resistance and 25(OH)D level in established diabetes patients?" (PMID 24868538, 2014). "Physical activity increases insulin sensitivity, while HFD has been shown to cause insulin resistance." (PMID 24997069, 2014). "This disease is a multistage process that begins as insulin resistance (IR), characterized by body inability to use properly its own insulin, and ends with exhaustion of the insulin-producing pancreatic ß-cells, thereby leading to hyperglycaemia." (PMID 25551102, 2014). "In vivo, it also suggested that the impaired insulin secretion was accompanied by insulin resistance in the high-fat diet rats." (PMID 24829924, 2014). "The result showed that triglyceride levels were similar and insulin-dependent KPD group had more serious insulin resistance than T2DM." (PMID 24829925, 2014). "To further investigate the regulatory mechanism that link hyperglycemia and insulin resistance, we investigated the levels of the major insulin-sensitizing adipokines—adiponectin and leptin —as well as insulin in plasma from STZ-induced diabetic mice." (PMID 25013896, 2014). "The onset is silent and often remains unrecognized for several years because insulin resistance can be compensated for by enhanced secretion of insulin from the pancreatic β-cells." (PMID 24896641, 2014). "Given the central role of insulin resistance in the pathogenesis of T2DM and obesity, measures of insulin sensitivity are very important diagnostic and research tools." (PMID 25106496, 2014). "Excess GC effects on the liver also contribute to increased hepatic glucose output and hepatic insulin resistance, which in combination with reduced insulin sensitivity in skeletal muscle, results in hyperinsulinemia and hyperglycemia." (PMID 24302625, 2014). "Individuals with insulin resistance have increased plasma insulin concentrations resulting mainly from increased insulin production, which is necessary to compensate for resistance to insulin’s actions in hepatic, adipose, and muscle tissues." (PMID 25246308, 2014). "Total T3 was positively correlated with the body mass index (BMI), the concentration of serum insulin, and the insulin resistance index (HOMA-IR) but negatively correlated with age, serum glucose, and high-density lipoprotein cholesterol (HDL-C)." (PMID 24936390, 2014).